PCNA (proliferating cell nuclear antigen)
Diseases named in the same sentence as PCNA in open-access papers (continued):
Sharing a sentence is not in itself a finding about the gene and the disease.
tumor (continued). "Moreover, the downregulation of DPY30 was associated with lower expression of PCNA, Ki67, cyclin A and H3K4me3 in DPY30-knockdown xenograft tumor tissues than control group appreciably." (PMID 37324189, 2023). "PCNA is a critical protein for DNA replication and tumour proliferation." (PMID 37859585, 2023). "The SHPRH (SNF2, histone linker, PHD, RING, helicase) subfamily belonging to ATP-dependent chromatin remodeling factor is the effective tumor-suppressor, which can polyubiquitinate PCNA (proliferating cell nuclear antigen) and participate in post-replication repair in human." (PMID 36987072, 2023). "Next, we performed PCNA immunostaining, which showed a significantly higher number of PCNA-positive cells in the tumor regions of the N-WASPKOG12D mice, suggesting an increased rate of proliferation of the epidermal keratinocytes in these mice as compared to the N-WASPHetG12D mice." (PMID 37760426, 2023). "PCNA migration towards the membrane of tumor cells might initiate the physical interaction between the NK cells and target cells, or the lytic state of other tumor cells attacked by NK cells." (PMID 37686697, 2023). "Notably, CHAF1A and PCNA expression were significantly upregulated in the EC tissues compared to non-tumor tissues." (PMID 37189802, 2023). "Moreover, novel inhibitors or strategies inhibiting tumor development or proliferation via targeting PTMs of PCNA require identification." (PMID 36776764, 2023). "In agreement with high PCNA expression in the UVB + TRE group compared to UVB mice, PCNA could be a hallmark of proliferation of damaged keratinocytes by TRE; associated with the tumor development observed in this group." (PMID 37049691, 2023). "PCNA is crucial for tumour cell DNA replication and is a marker for tumour proliferation." (PMID 37859585, 2023). "In the ex vivo PDE experiment, the combination of riluzole and fulvestrant was highly effective and more robust than either agent alone, with 80% (4/5) of primary tumor explants showing significant growth inhibition by the combination as measured by a reduction in PCNA." (PMID 37766843, 2023). "Moreover, the number of tumor cells with positive PCNA staining in EpiCD147-OE mice was almost two-fold greater than that in EpiCD147-WT mice." (PMID 35964097, 2022). "Moreover, we evaluated the proliferation of the tumor cells using PCNA as an important marker of proliferation, which has an important role in triggering the start of the cell cycle and boosting the G1-S phases of the cell cycle." (PMID 36308603, 2022). "Thus, the recognition of PCNA at the surface of tumor cells by splice-isoform 1 of NKp44 serves as a novel immune checkpoint through which tumors can evade immune destruction." (PMID 35563109, 2022). "PCNA and Ki-67 are molecular markers that are useful tools for studying cell proliferation, with their possible apparent expression in neoplasm indicating cell division and proliferation, and Cyclin D1is a protein that promotes proliferation and is mostly expressed during the G1-S phase transition." (PMID 35299600, 2022). "In addition, ZHX2 inhibited tumor growth in terms of the reductions in growth rate, tumor size and weight, and PCNA-positive cell numbers." (PMID 36232466, 2022). "V-125 had a limited effect on proliferation of tumor cells, visualized by PCNA expression." (PMID 34997154, 2022). "In order to assess the proliferative activity of implanted tumor cells, the tumor tissue sections were analyzed for the presence of Proliferating cell nuclear antigen (PCNA), which represents one of the key participants in DNA replication and subsequent cell division." (PMID 36139555, 2022).
tumor (continued). "To know more about the role of KIF18A in neoplasms, we studied two other proteins: Ki67 and PCNA." (PMID 35464837, 2022). "Patient-derived xenografts (PDXs) were subjected to tumor microarray and treatment screening with chemotherapies, either individually or in combination with the peptide R11-NLS-pep8; this peptide targets both membrane-associated and nuclear PCNA." (PMID 36430528, 2022). "Additionally, we also examined the expression of proliferating cell nuclear antigen (PCNA) protein in tumor tissue." (PMID 35269987, 2022). "Immunostaining revealed that the PCNA index decreased, which again proved that glutamine could indeed inhibit tumor growth." (PMID 35741311, 2022). "PCNA immunohistochemical staining was used to evaluate the proliferation status of tumor cells." (PMID 35116094, 2022). "Consequently, there were substantially less stained PCNA and Ki67 in tumours in circ‐0008003‐repressed cell group relative to those in NC‐treated H460 cell group." (PMID 33320427, 2022). "Furthermore, immunohistochemistry analysis confirmed that the nuclear expression of PCNA, a proliferative marker, was markedly reduced in these xenografic tumor-bearing ILK KO MKN1 cells." (PMID 35778385, 2022). "Immunohistochemical examination of the expression of PCNA showed that the number of proliferating tumor cells was significantly lower in the tumors from mice in the EVs-L-PGDS group compared with the groups treated with PBS (P < 0.001) or EVs-Vector (P < 0.01)." (PMID 35087591, 2022). "Furthermore, IHC assay demonstrated that QLD efficiently inhibited the expression level of PCNA in the xenograft tumor." (PMID 35782093, 2022). "The expressions of PCNA and Ki67 were also performed to check the proliferation of tumor cells." (PMID 35178457, 2022). "Importantly, pharmacological inhibition of mTOR or MEK lowered the abundance of PCNA, a marker of tumor cell proliferation, and subsequently suppressed cell growth and tumorigenesis in mouse model." (PMID 35437691, 2022). "Moreover, IHC staining showed high RHBDL2, Ki-67, and PCNA expression levels in tumor tissues with RHBDL2 upregulation." (PMID 36351890, 2022). "Then, PCNA staining was conducted to assess the effect of LL-37 on proliferation in tumor tissue." (PMID 35039485, 2022). "Increased PCNA expression, thus, promotes tumor cell proliferation." (PMID 35269987, 2022). "We further assessed the expression of KI67 and PCNA in the tumor tissues." (PMID 35635094, 2022). "PCNA expression in the PBT24-control tumor was significantly lower than in the SF8628-control." (PMID 36142368, 2022). "The expression of PCNA and Ki67 in xenograft tumor tissues was detected by IHC." (PMID 35177075, 2022). "In addition, immunohistochemistry showed that the expression of the proliferation-related protein PCNA in the tumour gradually decreased in the control group, and that of the low-dose and high-dose groups gradually decreased." (PMID 35517401, 2022). "PCNA can be used as a proliferation marker in cancer diagnosis to assess the proliferative activity of tumor cells, thus indicating that the administration of engineered bacteria can inhibit tumor proliferation." (PMID 36559282, 2022). "Importantly, pharmacological inhibition of mTOR or MEK lowered the abundance of PCNA, a marker of tumor cell proliferation, and subsequently suppressed ribosome biogenesis, cell growth and xenograft growth in mouse model." (PMID 35437691, 2022). "Additionally, small molecules targeting PCNA trimerization have also been designed and have been shown to be effective against tumour growth." (PMID 36360296, 2022).
tumor (continued). "While it was initially perplexing how NKp44 could detect the nuclear PCNA in tumor target cells, we further showed that PCNA is present on tumor cell surfaces and is recruited to the NK immunological synapse." (PMID 35563109, 2022). "Furthermore, the relative expression levels of proliferating cell nuclear antigen (Ki-67) and PCNA were increased in the tumor samples of Agr-treated groups compared with those of the control groups." (PMID 36591497, 2022). "PAP-AuNPs could increase the tumor inhibition rate and H&E and PCNA staining also confirmed that inhibition effects." (PMID 35363110, 2022). "In addition, E-cadherin and PCNA, essential biomarkers of tumor cell proliferation and migration, expression from the Cu-Cy group and X-PDT group showed significant differences in comparison to the control group." (PMID 34466749, 2022). "Tumor proliferation capacity could be evaluated through the expression of proliferating cell nuclear antigen (PCNA)." (PMID 36339607, 2022). "However, comparing the effect of the 5 mM DCA preparations, the impact of NaDCA on PCNA expression was significantly better in the PBT24 tumor." (PMID 36142368, 2022). "We observed that the tumor growth, along with the levels of Ki-67 and PCNA, were repressed by the depletion of MMP2-AS1, while the overexpression of MMP2 could reverse the effect in the nude mice." (PMID 35342412, 2022). "PCNA is closely related to cell proliferation activity, and it has been verified that the proliferation of tumor cells could be suppressed by down-regulating PCNA expression." (PMID 36575044, 2022). "Indeed, several studies show that epigenetic aberrations such as the loss of DNMT1 protein expression or DNMT1/PCNA/UHRF1 complex integrity are the source of genetic instability (deletion, translocation) and point mutations promoting tumor formation." (PMID 36278678, 2022). "EOC patients with advanced tumor grade (Grade 3) had higher PCNA expression." (PMID 36531044, 2022). "Furthermore, more PCNA positive cells in the tumor tissues were found when co-injected with SCD1-overexpressing fibroblasts." (PMID 36439884, 2022). "PCNA expression is high in many cancers, and its interaction with NKp44 inhibits the activation of NK cells and the lysis of tumor cells by NK cells; we showed that PCNA is expressed on the cell surface of some solid tumors but not on the cell surface of matched healthy tissues." (PMID 35563109, 2022). "The discrepancy between PCNA expression in vitro and in vivo may be explained by the involvement of other cell growth factors in tumor growth." (PMID 35453543, 2022). "PCNA also has a high level of expression in numerous tumor cells." (PMID 35401213, 2022). "Furthermore, we evaluated the expression of proliferation markers, including PCNA and Ki67, to further validate the inhibitory effects of different treatments on tumor growth." (PMID 35177075, 2022). "In addition to these proinflammatory factors, we also analyzed the expression of tumor proliferation-related proteins (PCNA and cyclin D1)." (PMID 33558702, 2022). "For the evaluation of the anti-tumor effect of V-A-mPD-1, we performed immunohistochemical assays, and the outcomes revealed that the V-A-mPD-1 strain markedly inhibited tumor cell proliferation by suppressing the expression of proliferating cell nuclear antigen (PCNA)." (PMID 36559282, 2022). "In addition, immunohistochemical analysis showed a significant reduction in proliferating cell nuclear antigen (PCNA) positive cells in tumor tissues of mice treated with a high dose of PC." (PMID 35447933, 2022). "Interestingly, the primary tumors from miR-659-3p injected mice expressed less proliferative markers PCNA and Ki67, indicating the tumor cells were less proliferative in vivo." (PMID 36038837, 2022).
tumor (continued). "The tumors were stained by the proliferation-related nuclear antigen Ki-67 and the sensitive marker of proliferative activity PCNA, which demonstrated that FAM83H-AS1 overexpression promoted tumor growth, while the loss of FAM83H-AS1 exerted the opposite effect." (PMID 36171592, 2022). "The current results that the WT/PyMT tumors showed higher stromal in and local invasiveness than the 211F/PyMT tumors suggest that Y211 phosphorylation of PCNA plays an active role in shaping the tumor microenvironment for tumor progression in addition to its traditional growth-promoting function." (PMID 35628489, 2022). "Interestingly, the immunofluorescence staining of the marker for proliferating cells, PCNA, showed that only a minority of proliferating tumor cells produced Trop2." (PMID 36077674, 2022). "Also the expressions of Ki-67 and PCNA in tumor tissues were further verified by performing immunohistochemistry." (PMID 33500536, 2022). "The control SF8628 tumor had significantly more PCNA-positive cells than the PBT24 control." (PMID 35216113, 2022). "PCNA staining was stronger in NFIB cKO tumor tissue, indicating higher proliferating activity." (PMID 35655758, 2022). "(J) The density of proliferating cell nuclear antigen (PCNA)-positive cells in tumor tissue." (PMID 34528509, 2021). "The expression levels of PKM2 and LDHA were significantly decreased together with β-catenin and proliferating cell nuclear antigen (PCNA) by KYA1797K treatment in the tumour area of the small intestine from Apcmin/+ mice compared with those of vehicle-treated mice." (PMID 33071283, 2021). "Downregulation of FBXO43 inhibits the tumor growth of BC by limiting its interaction with PCNA." (PMID 34645483, 2021). "Western blot result revealed that oe-ADAMTS9-AS1 markedly decreased the expression of tumor markers for proliferation and invasion, such as Ki67, PCNA, MMP-2, MMP-9, suggesting that oe-ADAMTS9-AS1 could reduce tumor proliferative, and invasive abilities." (PMID 34900984, 2021). "The treatment of ropivacaine repressed the cell growth of MDA-MB-231 cells in vivo, while miR-27b-3p inhibitor could reverse this effect, as shown by tumor size, tumor volume, tumor weight, and the levels of ki-67 and PCNA." (PMID 34126594, 2021). "Additionally, we further found POU2F2 ablation suppressed the expression of Ki67, PCNA, and N-cadherin in tumor tissues, suggesting the inhibition of tumor growth." (PMID 33832481, 2021). "Besides, the results of H&E and immunohistochemistry staining showed that in hsa_circ_0058493 knockdown group, the positive rate of Ki67, PCNA (tumor proliferation marker) and Bcl-2 (tumor apoptosis marker) in vivo was markedly reduced compared with sh-NC." (PMID 34888309, 2021). "The Ki-67-positivity rates and PCNA-average integrated optical densities were lower in the anlotinib group than in the positive control group, suggesting that tumor growth was inhibited in HNSCC PDX mice; moreover, anlotinib significantly inhibited tumor cell proliferation." (PMID 34955687, 2021). "PCNA expression can directly reflect the proliferation of tumor cells." (PMID 34257693, 2021). "Furthermore, IHC staining revealed that intratumoral injection of overexpressed circESRP1 enhanced the E-cadherin expression, but decreased the levels of PCNA, c-Myc, and Vimentin, indicative of lower aggressive capabilities of tumor growth and metastasis." (PMID 34775467, 2021). "As exhibited by immunohistochemistry, the positive rates of SALL4, MMP-2, MMP-9, and PCNA proteins were decreased in tumor tissues of mice treated with exosomes, and these trends were further facilitated in the tumor tissues of mice treated with miR-15a agomir-exos." (PMID 34455417, 2021).
tumor (continued). "Finally, the expressions of PD-L1, CircCHST15, miR-155-5p, miR-194-5p, and proliferation-related factors (Ki67 and PCNA) in the tumor tissues were determined." (PMID 33777742, 2021). "Interestingly, there are several small molecules, including cell-penetrating peptides, targeting PCNA with promising results against breast cancer and other tumours." (PMID 33536086, 2021). "In addition, circ-PLEKHM3 overexpression enhanced curcumin-mediated promotion of c-caspase-3 and Bax protein expression, and reduction of PCNA protein expression in tumor tissues." (PMID 34784955, 2021). "Therefore, we used anti-PCNA and anti-Ki67 biomarkers to assess the proliferative activity and cell cycle progression of the tumor cells in different groups." (PMID 33596850, 2021). "Furthermore, we detected the GHR, PCNA (one tumour growth marker) and PI3K/AKT levels in tumours derived from cells silenced GHR and found the expression of GHR still decreased in the dissected tumours." (PMID 33492754, 2021). "In addition, the number of mitotic figures and the percentage of PCNA-positive tumor cells in the INT group were also higher than those in the IT group (respectively)." (PMID 34164110, 2021). "In addition, there was a significant positive correlation between COL11A1 and tumor proliferation markers (Ki-67 and PCNA) expression levels." (PMID 34183642, 2021). "Furthermore, we found that the proliferation marker PCNA was strongly upregulated in tumor sections from TM7SF2-OE nude mice group but PCNA expression was decreased in TM7SF2-KO nude mice group." (PMID 34667152, 2021). "The high expression of PCNA in Eya2−/− mice indicated the active proliferation of tumor cells." (PMID 34044846, 2021). "Moreover, the morphological changes and expression of Bcl-2 family proteins, MMP-2, and PCNA in tumor tissues were regulated by CR treatment in vivo, and were consistent with the in vitro results." (PMID 33946527, 2021). "SCF, TGFβ1, and PCNA-positive staining was widely observed in these tumor tissues." (PMID 34884420, 2021). "Additionally, the expression level of PCNA was significantly and positively correlated with tumor purity in CC (P=9.86 × 10-4, partial rho=0.197)." (PMID 34900731, 2021). "In addition, the outcomes of immunohistochemical experiment displayed that the positivity of oncogenic Ki-67, PCNA and N-cadherin was declined while that of tumor-suppressive E-cadherin was enhanced in tumors with the interference of LINC01559." (PMID 33824282, 2021). "Furthermore, H&E, TUNEL, and PCNA staining on tumor sections were conducted to confirm the synergistic and amplified PDT effects." (PMID 34930284, 2021). "Results showed that the tumor tissue with FTH enforced expression increased the PCNA staining." (PMID 34965856, 2021). "Moreover, the proliferation markers Ki67 and PCNA protein expression in xenograft tumor samples was lower in the oe-ZNF750 groups than in oe-Con groups, whereas, it was higher expressed in sh-ZNF750 groups than in sh-Con groups." (PMID 35003347, 2021). "Taken together, these results indicated that METTL8 expression was enhanced in LSCC, which could promote tumor growth dependent on PCNA, c-myc, and Cdc25c." (PMID 33816462, 2021). "In our study, we observed that FBXO43 was involved in tumor growth and interacted with PCNA in BC." (PMID 34645483, 2021). "Similarly, NCRs can bind to tumor cell ligands such as PCNA to induce apoptosis of neoplastic cells." (PMID 33924213, 2021). "The inhibitory effects were confirmed by analyses of the levels of Ki67 and PCNA in tumour slices." (PMID 33951324, 2021). "We hypothesize that this may be either due to contact inhibition of cell growth in the tumor (PCNA is a well-known proliferation marker), or due to tumor hypoxia, it is assumed that the activity of the PCNA promoter is inhibited during hypoxia." (PMID 33804861, 2021).